IGHV7-4-1 (immunoglobulin heavy variable 7-4-1)
Description:
V region of the variable domain of immunoglobulin heavy chains that participates in the antigen recognition. Immunoglobulins, also known as antibodies, are membrane-bound or secreted glycoproteins produced by B lymphocytes. In the recognition phase of humoral immunity, the membrane-bound immunoglobulins serve as receptors which, upon binding of a specific antigen, trigger the clonal expansion and differentiation of B lymphocytes into immunoglobulins-secreting plasma cells. Secreted immunoglobulins mediate the effector phase of humoral immunity, which results in the elimination of bound antigens. The antigen binding site is formed by the variable domain of one heavy chain, together with that of its associated light chain. Thus, each immunoglobulin has two antigen binding sites with remarkable affinity for a particular antigen. The variable domains are assembled by a process called V-(D)-J rearrangement and can then be subjected to somatic hypermutations which, after exposure to antigen and selection, allow affinity maturation for a particular antigen.
Synonyms: IGHV7-41; IGHV741
Gene: Immunoglobulin variable (V) gene on chromosome 14 (106,025,145 to 106,025,630, reverse strand). Ensembl gene ENSG00000282122.
Subcellular location: Secreted; Cell membrane
Gene Ontology:
Molecular function: antigen binding
Biological process: immunoglobulin mediated immune response
Cellular component: extracellular region; plasma membrane
Homologues: Orthologues: macaque IGHV7-4-1 (73% identical), mouse Ighv9-3 (71% identical), mouse Ighv9-1 (69% identical), mouse Ighv9-2 (69% identical), mouse Ighv9-4 (65% identical), rat AABR07065789.1 (61% identical). Paralogues in human: IGHV7-81 (85% identical), IGHV1-3 (79% identical), IGHV1-2 (77% identical), IGHV1-18 (76% identical), IGHV1OR15-1 (75% identical), IGHV1-46 (73% identical), IGHV1-69 (71% identical), IGHV1-69D (71% identical), IGHV1-58 (69% identical), IGHV1-24 (68% identical), IGHV1-45 (68% identical), IGHV1OR21-1 (66% identical), and 65 more.